POSTN (periostin)
Diseases named in the same sentence as POSTN in open-access papers (continued):
Sharing a sentence is not in itself a finding about the gene and the disease.
tumor (continued). "In this study we investigated immunophenotypic expression of periostin in a wide range of primary tumours and tumour-like lesions of bone as well as in bone secondaries and metastatic osteosarcomas." (PMID 30202513, 2018). "Other studies have shown that high expression of POSTN in tumor stroma is related to Gleason score, the stage of the tumor, and the degree of malignancy." (PMID 29946533, 2018). "POSTN is expressed not only during embryogenesis or pathogenesis (including neoplasia, tissue repair, and cardiac injury) but also in various organs, particularly fibroblast-rich connective tissues such as the skin or breast." (PMID 30574417, 2018). "Since POSTN levels in tumor tissues show relationship with prognosis in many cancers, several studies have analyzed if POSTN levels in serum correlate with cancer prognosis." (PMID 29946533, 2018). "Knockdown of periostin inhibited outgrowth and invasion of mesenchymal tumor cells upon chemotherapy." (PMID 29507310, 2018). "Together, these data demonstrate that chemotherapy induces upregulation of periostin in tumor cells and expansion of mesenchymal tumor cells with an increased expression and activity of MT-MMPs." (PMID 29507310, 2018). "In agreement with the reduction of tumor volume, the significantly decreased expression of POSTN, α-SMA and PCNA, and the apparently increased expression of E-cadherin and cleaved-Caspase-3 were observed." (PMID 30400797, 2018). "In this study, we firstly demonstrate that activated HSCs promote the tumor progression of residual HCC after sublethal heat treatment through the release of POSTN." (PMID 30400797, 2018). "Periostin is also expressed in a number of cancers where it is thought, by various mechanisms, to play a role in tumour progression." (PMID 30202513, 2018). "POSTN interacts with tumor cells through integrin receptors and elicits a plethora of signaling pathways in tumors cells related to cell proliferation, cell survival, or cell migration." (PMID 29946533, 2018). "In summary, POSTN is a multifunctional protein deregulated in many solid tumors, which modulates tumor cell behavior in many ways." (PMID 29946533, 2018). "Together, these data indicate that periostin in tumor cells is functionally important for chemotherapy induced mesenchymal tumor cell expansion, which consequently causes disruption of basement membrane and invasion." (PMID 29507310, 2018). "To understand the role of periostin in vivo, we knocked down human periostin in MCF10DCIS tumor cells using a doxycycline (dox)-inducible shRNA system." (PMID 29507310, 2018). "Periostin expression in the cytoplasm or nucleus of carcinoma cells correlated with tumor size and expression of PR." (PMID 29161296, 2017). "H&E findings indicated that tumor size was decreased in the periostin knockdown group as well as the number of nodules in tumor-bearing mice, while IHC data showed low levels of periostin, Twist and Snail expression in the periostin knockdown group." (PMID 28977942, 2017). "Periostin plays an important role in tumor development and is involved in carcinoma cell epithelial-mesenchymal transition (EMT), whereby mature epithelial cells undergo phenotypic morphological changes and become invasive, motile cells." (PMID 28977942, 2017). "Our IHC results confirmed TCGA data, as we detected strong cytosolic staining of periostin in higher-grade tumor specimens." (PMID 28977942, 2017). "We found that knockdown of periostin in PSCs significantly inhibited tumor growth and reduced tumor volumes and weights of xenografts in nude mice." (PMID 29163770, 2017). "Periostin expression in these cancers is well correlated with poor prognostic tumor features and poor outcome." (PMID 29161296, 2017). "All the tumor samples showed increased protein and mRNA levels of periostin compared with matched normal tissues." (PMID 29163770, 2017).
tumor (continued). "The detection of POSTN by the immunohistochemical (IHC) staining of tumor lesions by anti-POSTN mAbs targeting the fasciclin domain, which can inhibit integrin-mediated cell migration in vitro, has also been reported." (PMID 29065446, 2017). "In fact, the disruption of periostin in vivo shows a reduction in the recruitment of tumor-supportive TAMs (M2 subtype), inhibition of tumor growth, apoptosis of GSCs, and increase of survival in a xenograft mouse model." (PMID 28740831, 2017). "It has been shown that the patients with tumor exhibiting high-level periostin expression showed a significantly shorter survival time." (PMID 28088789, 2017). "Periostin not only serves as a prognostic factor for clinical outcome but also plays a role in resistance in several tumor cell types." (PMID 28754000, 2017). "In human MCF-10A mammary breast cells, periostin-overexpression enhances tumor growth and metastasis to the lung." (PMID 29161296, 2017). "Recent studies revealed that periostin is involved in tumor development and progression and its overexpression in cancer-associated stroma and/or in cancer cells has been associated with poor clinical outcome in various types of human cancer." (PMID 29161296, 2017). "In summary, stromal POSTN expression in primary tumor tissues independently predicted an unfavorable prognosis of CRC patients after the adjustment with covariates including TNM stage and postoperative chemotherapy." (PMID 26556874, 2016). "Periostin has a major role in carcinogenesis and tumor progression in a number of malignancies besides its role in bone metabolism." (PMID 27716740, 2016). "Beside, the nude mice tumor immunohistochemical staining showed fewer capillary-like vessels in POSTN-silenced group." (PMID 27223086, 2016). "Emerging evidences suggest that periostin is overexpressed in various types of human cancers and further results in accelerating migration and invasion abilities of tumor cells." (PMID 27034956, 2016). "The purpose of this study is to determine the role of POSTN in tumor angiogenesis and explore the precise mechanisms." (PMID 27223086, 2016). "A number of recent studies have shown that POSTN is capable of promoting tumor progression in many cancers." (PMID 27602954, 2016). "The highest relative mRNA expressions of POSTN were observed in malignant adjacent cancer stromal area among distal regions and tumor cells." (PMID 26716408, 2016). "Together, these findings suggested that POSTN promoted tumor angiogenesis mainly via Erk/VEGF signaling." (PMID 27223086, 2016). "Kaplan-Meier and log-rank tests revealed that patients with periostin present in MIBC cells had significantly higher risks for tumor progression and disease-specific mortality." (PMID 26981774, 2016). "Although our data verified that the expression of POSTN was slightly increased in tumor cells, CAFs were demonstrated to be the principal source of POSTN." (PMID 26857387, 2016). "Taken together, these data suggests that POSTN plays an important role in tumour formation and metastasis, being either expressed by the tumour cells or the surrounding stroma." (PMID 26930720, 2016). "Periostin is overexpressed in many human cancers, and high periostin levels have been correlated with tumor proliferation, cell motility and invasion, metastasis, angiogenesis, evasion of apoptosis, clinical stage, and survival outcome." (PMID 26981774, 2016). "We found that the differences between 3 mg/kg/d group and 4 mg/kg/d group in tumor size, the expression of POSTN, M-CSFR, and TGF-β and the infiltration of TAMs into hypoxic areas were not significant." (PMID 27602954, 2016). "Together, our results suggest that POSTN promoted tumor angiogenesis in PaC by stimulating the proliferation, migration and invasion of HUVECs." (PMID 27223086, 2016). "Last but not least, we have identified TGF-β3 by screening a panel of cytokines as the key regulator of POSTN expression in tumor microenvironment." (PMID 26857387, 2016).
tumor (continued). "The clinical correlation of POSTN expression location in epithelial ovarian carcinoma cell or tumor stroma cells is still controversial." (PMID 26716408, 2016). "The matrix-specific protein POSTN plays a functional role in the regeneration of tissues such as bone and heart, and promotes wound healing and tumor invasion." (PMID 26857387, 2016). "Not surprisingly, the volume and weight of subcutaneous xenografts were decreased in nude mice derived from the POSTN knockdown group as insufficient nutrients were supplied for tumor growth." (PMID 27223086, 2016). "In a previous study, tumor POSTN expression was shown to significantly promote intraperitoneal tumor metastatic growth in immunodeficient mice by increasing tumor angiogenesis and decreased tumor cell apoptosis." (PMID 26716408, 2016). "Of note, periostin participates in tumor development promoting cellular adhesion and enforcing tumor cell motility throughout the interaction with integrins αγβ3 and αγβ5." (PMID 26809067, 2016). "The results showed patients with high POSTN expression in both stroma and tumor had the shortest OS and PFS among other groups." (PMID 26716408, 2016). "Blocking interactions between periostin and integrin αv, using an anti-integrin αv antibody, attenuated skin allergic inflammation in a murine model." (PMID 26890265, 2016). "We have identified TGF-β3 by screening a panel of cytokines as the key regulator of POSTN expression in tumor microenvironment." (PMID 26857387, 2016). "Based on these observations, we aim to determine the role of POSTN in mediating tumor angiogenesis of PaC and its potential clinical significance." (PMID 27223086, 2016). "In patient samples, periostin expression at the tumour cell–stromal interface correlates with poor overall and disease-free survival." (PMID 25345775, 2015). "To further confirm that the inhibition of tumour cell invasion was directly modulated through reduced periostin expression, we immunodepleted periostin from CAFs-conditioned medium and observed a similar reduction in invasion (p < 0.05)." (PMID 25345775, 2015). "Previous studies revealed that POSTN plays an important role in tumor development and is up-regulated in a wide variety of cancers." (PMID 25874882, 2015). "Periostin is also required to initiate alteration of the extracellular matrix, creating a niche environment that allows tumour invasion and proliferation." (PMID 26543579, 2015). "siRNA-silencing of POSTN in CAFs suppressed periostin expression and resulted in a > 50% suppression of tumour cell invasion in Transwell assays (p < 0.05)." (PMID 25345775, 2015). "This is in accordance with the increased occurrence of tumor blood vessel in metastases of periostin-overexpressing 293T cells." (PMID 26539408, 2015). "Patients with high levels of periostin staining in the resected tumours experienced the shortest mean time to recurrence of 47.45 months (median 38 months; p = 0.006)." (PMID 25345775, 2015). "Taken together, these results suggest that CSCs are essential for metastatic colonization and that CSCs induce stromal fibroblasts to secrete POSTN in the metastatic niche to support tumor cell outgrowth by augmenting the Wnt signaling pathway." (PMID 26086719, 2015). "Our data show that periostin expression is highly correlated with the CaP tumor aggressiveness, which supports our previous discovery." (PMID 25781169, 2015). "Periostin is a matricellular protein with known functions in osteology, oncology, cardiovascular and respiratory systems in tissue remodeling, tumor metastasis, and various inflammatory settings." (PMID 25658308, 2015). "The periostin staining was observed mainly in peritumoral stromal cells and in some cases in tumor epithelial cells though the stronger staining was found in peritumoral stromal cells." (PMID 25781169, 2015). "Tumor cell survival was promoted as periostin binds to αvβ3-integrin, enhancing the PKB/AKT pathway at secondary sites." (PMID 26539408, 2015).
tumor (continued). "Its functional role in cancer is not clear, although expression correlates with poor outcome in several cancers, suggesting a tumour-promoting effect, and, consistent with this, periostin has been reported to modulate a number of the hallmarks of malignancy." (PMID 25345775, 2015). "Yet, while an equal amount of micrometastases was detected in the first days after intraportal injection, the further outgrowth of these cells was dependent on tumor cell-derived periostin." (PMID 26539408, 2015). "Periostin, keratin-1, nm-23 protein, etc., were up-regulated in tumour stroma; HSP 70, keratin-19, Rho GDP dissociation inhibitor (GDI) β, superoxide dismutase, etc., were down-regulated in tumour stroma." (PMID 26184160, 2015). "Increasing evidence has demonstrated that periostin actively contributes to tissue injury, inflammation, fibrosis and tumor progression." (PMID 25658308, 2015). "This was accompanied by a reduced αSMA and periostin expression within the primary tumour, thus suggesting that DMOG treatment suppresses CAF activation in vitro and in vivo." (PMID 26323721, 2015). "The upregulation of periostin has been observed in cutaneous wound healing, cutaneous fibrosis and in tumor progression." (PMID 25369801, 2015). "Recombinant periostin was added to tumour cells and phosphorylation of Akt was observed at 30 min post-stimulation, which persisted for at least 120 min." (PMID 25345775, 2015). "In consistent with our previous observation, the periostin staining was observed mainly in peritumoral stromal cells and in some cases in tumor epithelial cells though the stronger staining was found in peritumoral stromal cells." (PMID 25781169, 2015). "High expression of periostin localized in either tumor epithelia or peritumoral stroma was observed consistently as previous reports." (PMID 25781169, 2015). "Periostin is involved in remodelling of the ECM to support tumour development, invasion and metastasis." (PMID 25345775, 2015). "We found that CAFs express high periostin levels in vitro and in vivo, and activate tumour cell PI3K–Akt signalling through integrin binding." (PMID 25345775, 2015). "Periostin is a newly identified mediator of the inflammatory process and seems to play a role in collagen fibrogenesis and tumor development." (PMID 25221676, 2014). "In poorly metastatic tumors, fibronectin (FN1) and periostin (POSTN) are secreted by the tumor cells, whereas in highly metastatic tumors, they are secreted by both the tumor cells and the stromal cells." (PMID 24618895, 2014). "Decorin, mimecan, hemoglobin subunit alpha, hemoglobin subunit beta, and keratin type I cytoskeletal 19 were upregulated in normal tissue, whereas periostin and versican core protein were upregulated in phyllodes tumor tissue." (PMID 25400079, 2014). "These analyses revealed that decorin was expressed at lower levels, whereas periostin expression was upregulated, in phyllodes tumor tissues and cancer cells." (PMID 25400079, 2014). "The mRNA levels of periostin, another TGFβ-inducible factor important for tumor progression, tended to be lower in the former group of animals being the difference at the limit of statistical significance (p = 0.06)." (PMID 24797128, 2014). "Periostin has been reported to promote tumor angiogenesis, migration, and metastases, and its overexpression has been shown to enhance invasion and anchorage-independent growth and spread in oral squamous-cell carcinoma." (PMID 24146092, 2014). "Decorin expression in normal tissues was higher than in tumor tissues (P < 0.001, Wilcoxon signed-rank test; n = 35), whereas periostin expression was lower in normal tissues (P = 0.005, Wilcoxon signed-rank test; n = 35)." (PMID 25400079, 2014). "There are a number of studies identifying periostin as overexpressed in a wide variety of tumor tissues including breast, pancreas, ovary, colon and head and neck." (PMID 23372733, 2013).
tumor (continued). "Using immunohistochemistry, the present study showed that periostin was only located in the mesenchymal tissue surrounding the tumor cells." (PMID 24273600, 2013). "POSTN (periostin) is a secreted cell adhesion protein which plays an important role in tumor development and is upregulated in several types of cancers." (PMID 23805239, 2013). "In the present study, periostin expression was detected in the tumor, paratumor and normal tissues, and the clinical significance of periostin in the progression and development of NSCLC was observed." (PMID 24273600, 2013). "As an ECM protein, POSTN has been implicated in the induction of the EMT during development, inflammation and tumor progression." (PMID 24009721, 2013). "The majority of analyses have shown that periostin stimulated tumor growth by connecting with integrins, particularly αvβ3, αvβ5 and α6β4." (PMID 24273600, 2013). "Several reports have recently revealed that the ECM proteins fibronectin, tenascin-C, periostin and versican play essential roles as components of the metastatic niche for tumor-initiating cells that invade the lungs." (PMID 23951338, 2013). "Periostin protein levels of the tumor, paratumor and normal tissues of 49 NSCLC patients were detected in the present study." (PMID 24273600, 2013). "As a component of the extracellular matrix, Periostin interacts with integrin molecules that activate the PI3K signaling pathway in tumor cells." (PMID 24349533, 2013). "Tumour-derived TGF-β3 was shown to initially induce POSTN production in CAFs within pulmonary metastases." (PMID 24216702, 2013). "Recent studies have revealed that periostin plays an important role in tumor epithelial-mesenchymal transition, tumor angiogenesis, and tumor development." (PMID 23056395, 2012). "POSTN expression in the stromal and epithelial compartments of the tumor both correlated with PSA progression-free survival or overall survival, albeit in a different manner." (PMID 23273263, 2012). "To know the role of periostin in tumor lymphangiogenesis in vivo, we confirmed the correlation between periostin expression and the number of lymphatic vessels in a tumor xenograft model in nude mice." (PMID 22952986, 2012). "Both stromal and epithelial POSTN expressions were significantly increased in tumor tissues as compared to normal adjacent tissues (p<0.000 and p=0.001, respectively)." (PMID 23273263, 2012). "In humans and in GEMM, highest periostin expression is always found on the activated front of the stroma; between normal pancreas and the tumor." (PMID 23060813, 2012). "In conclusion, we have demonstrated that periostin has a novel function as a direct and/or indirect promoter of tumor lymphangiogenesis." (PMID 22952986, 2012). "We previously injected control or periostin-overexpressing HNSCC cells subcutaneously into nude mice and found that transplanted periostin-overexpressing cells produced comparatively larger tumor volume after 28 days than did empty vector-transfected cells." (PMID 22952986, 2012). "Periostin protein was observed to be expressed significantly higher in cancerous tissues than adjacent-tumor tissues." (PMID 23056395, 2012). "In the present study, we demonstrate a novel action of periostin: the direct and indirect promotion of tumor lymphangiogenesis." (PMID 22952986, 2012). "Distinct stromal and epithelial staining characteristics allowed for absolutely certain evaluation of POSTN staining in the selected tumor and peritumor tissue specimens." (PMID 23273263, 2012). "The expression of POSTN by tumor epithelial cells was significantly lower than what was observed in stromal cells (p=0.003)." (PMID 23273263, 2012). "Since POSTN was reported as an extracellular protein, the staining of the stroma around the tumor implied that the tumor cells secrete POSTN to tumor stroma." (PMID 22280838, 2012).